IL21 (interleukin 21)
Diseases named in the same sentence as IL21 in open-access papers (continued):
Sharing a sentence is not in itself a finding about the gene and the disease.
influenza (continued). "Interestingly, IL-21R levels in CD8 T lymphocytes remained unaltered, implying that mechanisms other than IL-21 are involved in the generation of influenza-specific CD8 T cells." (PMID 24236161, 2013). "In aging HIV-infected and uninfected women, activated CD4 and pTfh cells may compromise influenza vaccine-induced antibody response, for which a mechanism of TNFα-mediated impairment of pTfh-induced IL-21 secretion is postulated." (PMID 24236161, 2013). "The observed alteration of TIGIT+ pTfh, AM B cell, and CD11b+ monocyte population frequencies in IL-21–treated animals represents immune correlates of influenza vaccine responses in SIV+ aged RM and may be indirectly or directly modulated by IL-21 immunotherapy." (PMID 34491910, 2021). "Furthermore, we found that there was a trend (P = 0.0727) of increased TIGIT expression on pTfh cells in IL-21–treated animals, and influenza HAI titers day 14 after B1 correlated with both TIGIT+CD4+ Tcm (r = 0.6808, P = 0.0120) and TIGIT+ pTfh (r = 0.7387, P = 0.0112) cells." (PMID 34491910, 2021). "To investigate the immunomodulatory potential of IL-21 aimed at improving influenza vaccine responses in aged SIV+ RMs, we compared serum influenza HAI titers among aged SIV+ IL-21–untreated (n = 4) and aged SIV+ IL-21–treated (n = 8) RMs." (PMID 34491910, 2021). "Likewise, seasonal influenza vaccines elicit an antigen-specific cTfh1 response;16,18,25,28 and whereas the cTfh1 cells activated following vaccination are able to provide help for antigen-loaded influenza-specific mBCs in vitro, they produce insufficient IL-21 to support naive B cell activation." (PMID 33763653, 2021). "Strikingly, hybrid Th1/Tfh cells (ICOS+CXCR3+CXCR5+) did correlate with antibody levels in influenza, where they were also shown to contain IFN-γ+IL-21+ T cells." (PMID 32634740, 2020). "In fact, a previous study using tetramer staining and activation-induced marker (AIM) assay demonstrated an expansion of the Ag.pTfh population post influenza vaccination, with co-expression of ICOS and CD38 and IL-21 production in young HCs." (PMID 31100059, 2019). "Administration of the novel virus-like particle based vaccine elicited influenza-specific CD4+ and CD8+ T-cell responses and the induction of the cytokines IFN-γ, IL-17A, IL17F, IL-5, IL-13, IL-9, IL-10 and IL-21." (PMID 30573748, 2018). "These cells can exert helper function to influenza-specific B cells in CD40L- and IL-21- dependent fashion." (PMID 24755693, 2014). "Of interest however, B cell responses to influenza, or immunogens that contain a TLR7 agonist, have been shown to be less dependent on IL-21." (PMID 22792401, 2012). "Previous studies from our lab identified functional defects in antigen-specific peripheral T follicular helper cells (pTfh), characterized by low IL-21 and high IL-2 production, contributing to non-responsiveness to the influenza vaccine in both aging and HIV." (PMID 41801310, 2026). "We observed that IL-21 partial agonism induced a range of flu-specific and non-specific antibody production upon vaccination." (PMID 37339051, 2023). "In this study, we demonstrate that IL-21 immunotherapy significantly improves influenza vaccine responses in aged SIV+ RMs but not young SIV+ RMs." (PMID 34491910, 2021). "In HIV seronegative individuals, the emergence of blood ICOS+CXCR5+CXCR3+ TFH that are able to produce IL-21 correlated with influenza-specific B cell responses and blood ICOS+IL-21+ influenza-specific TFH expand after immunization and correlate to antibody responses." (PMID 28082992, 2016). "Comparing influenza HAI titers among SIV+ IL-21–treated RMs to young SIV– animals revealed no significant day 14 after B1 differences, suggesting that IL-21 treatment improves post-B1 influenza HAI titers in aged SIV+ animals to levels comparable with SIV– healthy young controls." (PMID 34491910, 2021).
influenza (continued). "Several studies have also noted decreased production of IL-21 from Tfh cells in HIV+ subjects compared to healthy controls, and that this drop is correlated with both lower frequencies of memory B cells and lower specific antibody titres post-influenza vaccination." (PMID 36845567, 2021). "We found that IL-21hi cells exhibited the highest expression levels of Il21, Bcl6, and Cxcr5 but not Foxp3, compared with other cell populations, suggesting that TRH cells but not regulatory T cells express IL-21 in the lung after influenza infection." (PMID 38345472, 2024).
lymphoma (27 papers, 2011 to 2026). A malignant (clonal) proliferation of B- lymphocytes or T- lymphocytes which involves the lymph nodes, bone marrow and/or extranodal sites. "Selected cytokines may result pivotal in the orchestration of such pathogenic DLBCL microenvironment, where deprivation of IL-21 or addiction to IL-10 can support tumour survival and modulate PD-L1 levels in the lymphoma cells." (PMID 34572910, 2021). "Similar to the CD19IL15 CAR-NK cells in lymphoma model, cytokine-armed NK cells (IL-21 and IL-15 NK cells) showed more significant tumor control than NT-NK cells." (PMID 40027823, 2025). "The greater an individual lymphoma expresses αIgM target genes, the greater it will also express IL21 or CD40L regulated genes." (PMID 23253402, 2012). "IL-21, that was shown to be produced by Th17 cells in eyes with lymphoma, has already been shown to act on B cells." (PMID 21949734, 2011). "Intracellular cytometry showed the presence of Th17 cells, that is, CD4+ T cells coproducing IL-17 and IL-21, in eyes with lymphoma." (PMID 21949734, 2011). "By studying tumor-immune dynamics through simulations, we found better-performing NK cell products possessing superior cellular properties including higher viability, cytotoxicity, and serial killing capacity, i.e. CD19IL15 CAR-NKs in treating lymphoma and IL21 NKs in treating GBM." (PMID 40027823, 2025). "Devangi and colleagues observed that IL-21 induces apoptosis in B cells and also inhibits growth and induces apoptosis in lymphoma cells, suggesting that IL-21 may also promote apoptosis in SGECs." (PMID 39050857, 2024). "In addition to stabilizing and extending the half-life of IL-21, the αCD20-IL-21 enhanced IL-21R-mediated signaling which results in direct lymphoma cytotoxicity and increased NK cell-mediated cytotoxicity." (PMID 38638431, 2024). "Indeed, cytotoxic activities of IL-21 have been observed for inappropriately activated B cells and some lymphoma cells, by induction of apoptosis and growth arrest." (PMID 34572910, 2021). "On another hand, IL-21 might also become toxic for lymphomas by expanding and enhancing tumour-infiltrating cytotoxic CD8+ cells and NK cells." (PMID 34572910, 2021). "However, pathology slides of such lymphomas also include plasmocytes, immature B lymphocytes, chemokines, immunoglobulins, IL-21, and IL-6, thus originating in the largest part by TFH tumors." (PMID 33114418, 2020). "It should be noted however that IL-21 can trigger apoptosis of IL-21R-expressing lymphomas." (PMID 28615039, 2017). "In fact, IL-21 supports neoplastic cell proliferation and/or survival in anaplastic large cell lymphoma, Hodgkin's lymphoma, multiple myeloma, Waldenstrom macroglobulinemia, adult T cell leukemia/lymphoma, cutaneous T cell lymphoma, and Sézary syndrome." (PMID 25961061, 2015). "In addition, it appears that the anti-lymphoma effects of IL-21 are dependent on a mechanism involving the IL-21-activated STAT3 upregulation of c-Myc, in which c-Myc is a highly prognostic marker in DLBCL." (PMID 24959288, 2014). "However, opposite outcomes are possible in more advanced stages of DLBCL, where TFH-derived IL-21 might elicit anti-lymphoma activities through at least two different mechanisms (right)." (PMID 34572910, 2021). "In addition, IL-21 exerts divergent effects on different lymphoid cell leukemia and lymphomas, as it may support cell proliferation or on the contrary induce growth arrest or apoptosis of the neoplastic lymphoid cells." (PMID 25961061, 2015). "Consistent with the development of an AITL condition, the transcriptome of the lymphoma samples obtained from Trp53ER/ER;Vav1ΔC/ΔC mice includes the upregulation of AITL‐specific genes such as Bcl6, Maf, Il21, Pdcd1, and Icos." (PMID 35895495, 2022). "CD19 CAR NK cells expanded using IL21-expressing feeder B cells were more cytotoxic against CD19+ lymphoma cells and displayed higher tumor burden control in two lymphoma xenograft models." (PMID 35008348, 2021).
lymphoma (continued). "IL-21 is upregulated in AITL and its knockdown has been shown to inhibit lymphoma genesis in a model of Swiss Jim Lambart (SJL) mouse." (PMID 33114418, 2020). "The cytokine interleukin-21 (IL-21) has been reported to be pro-apoptotic in DLBCL cell lines and is being explored as a new therapeutic strategy for this type of lymphomas." (PMID 32704112, 2020). "This revealed that artesunate exhibited broad activity across the lymphoma cell lines and potently affected cell growth, whereas it had limited effect in normal B-cells activated with CD40L alone or in combination with IL21." (PMID 29458389, 2018). "In conclusion, we demonstrated that IL-21 engineered, CD19-specific CAR-NK cells showed enhanced anti-tumor efficacy against CD19+ lymphoma cells both in vitro and in vivo settings, as well as increased persistence in a mouse xenograft model of lymphoma compared to IL-15 engineered CAR-NK cells." (PMID 40176196, 2025). "CAR-21 NK cells showed similar immunophenotypic profiles compared to CAR-15 NK cells, while IL-21 engineered CAR-NK cells exhibited significantly increased persistence and superior anti-tumor efficacy against CD19+ Raji lymphoma cells both in vitro and in vivo." (PMID 40176196, 2025). "These IL-21-impaired TFH cells in DLBCL may also promote a cytokine switch towards IL-10 production by TFR cells, further contributing to lymphoma maintenance and progression." (PMID 34572910, 2021). "Since rIL-21 (human) does not efficiently stimulate murine IL-21R, murine IL-21 (mIL-21) was used to test combinations with rituximab in disseminated lymphoma models using HS Sultan cells and Raji cells." (PMID 23825648, 2013). "Additionally, we were unable to show ex-vivo ADCC or NK cell activity using NK cells from mice bearing lymphoma and treated with rituximab+IL-21 (data not shown)." (PMID 23825648, 2013). "Contrarily, clinical studies showed that IL-21 can promote the proliferation of Hodgkin lymphoma, EBV transformed lymphomas and ALK-positive anaplastic large cell lymphoma suggesting that blocking the effect of IL-21 may be a potential therapeutic approaches in these lymphoma subtypes." (PMID 35529882, 2022).
breast carcinoma (25 papers, 2014 to 2025). "They suggested that the variants of ERCC2, TLR4, IL-2, IL-6, and IL-21 genes had associations with breast cancer prognosis respectively." (PMID 25075970, 2014). "Indeed, IL21 producing Tfh cells are known to be associated with formation of tertiary lymphoid structures in human breast cancer patients in a CXCL13-dependent fashion." (PMID 31756235, 2019). "We plan to conduct multicentre studies in the future to improve the statistical reliability and ensure a more representative patient group for the evaluation of IL-21 and IL-22 as potential immune markers in breast cancer." (PMID 40729006, 2025). "The study involved 60 women with breast cancer and 20 women with benign breast lesions, and the analysis of IL-21 and IL-22 protein concentrations was performed using the enzyme-linked immunosorbent assay (ELISA) method." (PMID 40729006, 2025). "Future research involving larger, well-balanced cohorts and multicentre collaboration is necessary to validate the potential role of IL-21 and IL-22 as biomarkers and to better understand their involvement in the breast cancer pathogenesis." (PMID 40729006, 2025). "Previous studies have shown an overexpression of the IL-21 gene in breast cancer tissue in patients with advanced or metastatic disease." (PMID 40729006, 2025). "IL-21 is another important cytokine that modulates the immune response within the TME of breast cancer." (PMID 39456897, 2024). "Higher expression levels of IL-12, IL-21, and IFN-γ were associated with better outcomes, especially in patients with basal-like breast cancer." (PMID 39456897, 2024). "It seems that Th17 cells by creating inflammatory conditions through the secretion of cytokines, including IL-22, IL-17, TNF-α, IL-21, and IL-6, can significantly enhance breast cancer progression." (PMID 35248028, 2022). "DLN lymphocytes were antigen-sensitized with 4T1 mammary carcinoma 10 days prior to harvest, activated with B/I, and expanded in culture for 7 days with either IL-2, IL-21, IL-2/21, IL-7/15, or IL-7/15/21." (PMID 28146052, 2017). "DLN T cells activated with B/I and cultured with IL-2, IL-21, IL-2/21, IL-7/15 or IL-7/15/21 for 7 days were harvested and cultured for 24 h alone or with irradiated 4T1 murine mammary carcinoma cells to stimulate IFN-γ release." (PMID 28146052, 2017). "Also, the administration of plasmids expressing IL-21 exhibits significant antitumor activity, mediated by NK cell and T cells, against melanoma fibrosarcoma, renal cell carcinoma and mammary carcinoma subcutaneous head and neck squamous cell carcinoma." (PMID 38638431, 2024). "Their study demonstrated that the addition of IL-21 significantly increased strong cytotoxicity against trastuzumab-resistant breast cancer cells with the synthesis and secretion of IFN-γ and IL-2, after combining HER2-targeted CAR-T cells with trastuzumab-resistant HCC1954 and BT474 cells." (PMID 35935930, 2022). "In addition to their role in the melanoma, Th9 cells can play an antitumor role in breast cancer via IL-9 and IL-21." (PMID 32228589, 2020). "Furthermore, FOXP1 suppresses the antitumor function of interleukin 21 (IL-21) to stimulate the secretion of IFNγ from CD4+ T or CD8+ T cells in estrogen positive MCF-7 breast cancers." (PMID 31815635, 2019). "A recent study showed IL-21 and its receptor play an important role in breast cancer cells via proliferation, migration, and invasion, suggesting IL-21R could contribute to other diseases via similar mechanisms." (PMID 30728806, 2019). "In addition, the expression of the five signature cytokines is negatively correlated with tumor purity in breast cancer, especially for IL-17A, IL-21, and IL-26, which indicates that these cytokines are mainly derived from immune cells such as Th17 cells rather than tumor cells." (PMID 33102239, 2020).
breast carcinoma (continued). "The acute inflammatory IL signature, comprising IL-12, IL-21, and IFN-γ, demonstrated a significant prognostic impact, particularly within the basal-like breast cancer subtype." (PMID 39456897, 2024). "The acute inflammatory IL signature, comprising IL-12, IL-21, and IFN-γ, demonstrated a significant impact on MFS in the basal-like breast cancer subtype." (PMID 39456897, 2024). "Also, IL-21 could directly trigger NK cell-mediated cytotoxicity against breast cancer cells." (PMID 38106519, 2023). "Our previous work with breast cancer patients demonstrated that high levels of TGF-β, TNF-α, VEGF, IL-6, IL-8, and IL-10 correlated with poor prognosis, while IL-21 and CCL-2 are related to a better outcome." (PMID 36428939, 2022). "IL-9 and IL-21 can amplify the cytotoxic effect of CD8+ T cells, thus promoting an antitumor effect in breast cancer." (PMID 32228589, 2020). "In summary, an interaction between CD40 on MDA-MB231 breast cancer cells and CD40L on activated T cells increases the production of Th17 differentiating cytokines including TGF-β, IL-1β, IL-6, and IL-21." (PMID 25992978, 2015). "The analysis did not reveal any significant differences in the serum IL-21 concentrations in breast cancer patients, regardless of histological grade or molecular subtype." (PMID 40729006, 2025). "Similarly, IL-21 enhances the proliferation and function of NK cells and CD8+ T cells, boosting antitumor immune responses and reducing tumor burden in preclinical breast cancer studies." (PMID 39456897, 2024). "A recent study also showed that IL-21 increased the proliferation of IL-21R+ MDA-231 breast cancer cells but not that of other breast cancer cells." (PMID 30728806, 2019). "Also, Park reported that exogenous IL-21 directly increased the cytotoxicity and IFN-γ production of ex vivo expanded NK cells in coculture with breast cancer cells." (PMID 30223493, 2018). "A moderate negative correlation was observed between IL-21 and IL-22 serum levels in patients with benign breast lesions (rS = −0.663, p = 0.002), whereas no such correlation was found in patients diagnosed with breast cancer (rS = −0.109, p = 0.410)." (PMID 40729006, 2025). "The conducted research has shown that IL-21 promotes proliferation, invasion and migration of IL-21R + MDA-231 breast cancer cells, it does not show such strong properties against MCF-7 and ZR-75.1 cells, in which IL-21R expression is weak or negative." (PMID 34300224, 2021). "In an EMT-6 mammary carcinoma model IL-21 and mAb CTLA-4 combination therapy induced complete regression in half of the mice and noticeable delays in tumor growth for the rest of mice employed in the study, while the combination of IL-21 and mAb PD-1 displayed no noticeable effects." (PMID 38638431, 2024).
Sjögren’s syndrome (25 papers, 2008 to 2025). "The ICOS+PD-1+ cTfh cells and IL-21 producing CD4+CXCR5+PD-1+ T cells were also shown to be significantly higher in patients with Sjögren syndrome." (PMID 33465845, 2021). "Specifically, polymorphisms in either IL-21 or IL-21R genes have been identified that associated with SLE, RA, and primary Sjogren’s syndrome." (PMID 24600453, 2014). "Importantly, higher plasma IL-21 levels in patients with Sjögren’s syndrome and SLE compared to healthy individuals were also validated with this ultrasensitive assay." (PMID 37415982, 2023). "The correlation between IL-21 and severity of HBV-ACLF was investigated as other studies showed IL-21 has a critical role in Tfh proliferation/differentiation in HIV and Sjögren’s syndrome." (PMID 33868273, 2021). "Viewed together, these observations suggest the tissues of Sjogren's syndrome patients and NOD mice accumulate IL-21-producing B cell-helper T cell populations that can lack typical Tfh-associated features such as Bcl6 and CXCR5." (PMID 30190721, 2018). "In Sjogren's syndrome patients, CCR9+ CXCR5− T cells from the blood produced CXCL13 (in addition to IL-21 ), albeit at lower levels than was produced by CXCR5+ cells." (PMID 30190721, 2018).